ITGB3 (integrin subunit beta 3)
Diseases named in the same sentence as ITGB3 in open-access papers (continued):
Sharing a sentence is not in itself a finding about the gene and the disease.
cancer (123 papers, 2005 to 2026). A tumor composed of atypical neoplastic, often pleomorphic cells that invade other tissues. "As an important cell adhesion molecular, ITGB3 expression has been reported to be associated with LNM in several types of cancers." (PMID 35752862, 2022). "The most significantly up-regulated genes included TNFRSF25 (+3.4) and ITGB3 (+6.96), which have been shown to induce apoptosis, and have been associated with increased survival in cancer." (PMID 27586635, 2016). "ITGB3 plays a variety of essential functions in the progression of cancer and molecular reprogramming in the microenvironment." (PMID 39754146, 2025). "Research indicates that the expression levels of general stem cell markers (such as CD34 and CD73), genes linked to cancer stem cells (CD99 and ITGB3), and an embryonic stem cell marker (GGT1) are elevated within this subset." (PMID 41204265, 2025). "ITGB3 forms an αvβ3 heterodimer with ITGAV, which has been implicated in cancer cell adhesion, migration, and invasion." (PMID 40662366, 2025). "High ITGB3 expression was associated with the upregulation of several TGF-β-responsive genes and increased cell migration, both of which are important for cancer cell survival and dissemination." (PMID 39857240, 2024). "Specifically, our results showed an upregulation of Cldn7, Krt7, Axl, Tnc, Itgav, Itgb3, and Vcam1 in EpCAMhigh and EpCAMlow cancer cells relative to levels in full epithelial cancer cells." (PMID 39075581, 2024). "ITGB3 has been proposed to be critical for cancer metastasis, and related drugs are in clinical trials." (PMID 37950040, 2024). "Integrin β3 (ITGB3) was upregulated in all groups, especially carcinoma luminal A and TNBC patients." (PMID 39000458, 2024). "Protein docking analysis showed that 23 interface residues of ANGPTL3 interact with 23 residues of cancer-suppressing ITGB3 and ITGAV proteins." (PMID 37375208, 2023). "This study provides plentiful of not only clinical but also experimental evidence that cancer cell-derived ITGB3+ exosomes mediated CRC progression and metastasis and macrophage-derived ITGAM+ exosomes mediated CRC suppression." (PMID 37040507, 2023). "Both ITGA6 and ITGB3 are dominantly expressed in cluster 4, and considering that they are documented as specific cancer markers, it implied that cluster 4 originates from cancer cells." (PMID 37040507, 2023). "In the extracellular space, eSIRT2 deacetylates ITGB3 on aK416 involved in cell attachment and migration, leading to a promotion of cancer cell metastasis." (PMID 36453571, 2023). "Given that EM shares similar properties with malignant tumors, including the ability of cell migration, the transwell migration assay was further conducted to evaluate the effect of ITGB3/ITCH on the migration of ectopic ESCs." (PMID 37760946, 2023). "We further evaluated the function of ITGB3-enriched exosomes in vitro due to the importance of ITGB3 in cancer biology and its representative role in altered exosome subpopulation in CRC groups according to PBA tests." (PMID 37040507, 2023). "ITGB3 is a cell-adhesion receptor that plays a crucial role in the interaction between cells and extracellular fluid, and it proposed to be critical for cancer metastasis." (PMID 37375208, 2023). "Intriguingly, SIRT2 promoted cancer cell metastasis presumably via deacetylating multiple extracellular proteins including ITGB3 and collagens in the microenvironment." (PMID 36453571, 2023). "Intriguingly, SIRT2 promotes cancer cell metastasis presumably via deacetylating multiple extracellular proteins including ITGB3 and collagens." (PMID 36453571, 2023). "We confirmed the cancer-promoting role of ITGB3 and proved the correlation of ITGB3+ exosomes with CRC progression and metastasis in vitro and in vivo." (PMID 37040507, 2023). "ITGB3 was reported to play a central role in intracellular communication via extracellular vesicles, which was proposed to be critical for cancer metastasis." (PMID 35634447, 2022).
cancer (continued). "In BC cells, miR-30 inhibition enhances tumorigenesis and metastasis by targeting UBC9 and ITGB3 and osteomimicry of cancer cells by targeting RUNX2, ITGA5 and CDH11." (PMID 33800656, 2021). "One of these genes was ITGB3, an integrin involved in cell adhesion and ECM whose deregulation is associated with cancer metastasis." (PMID 34150764, 2021). "The upregulation of ITGAV and ITGB3 can make the cancer cells resistant to chemotherapy by different groups." (PMID 34680783, 2021). "Specifically, we discovered a novel protein complex, HDGF-LGR5, that adaptively responded to MAPKi to enhance cancer cell stemness, which was up- or downregulated by the inhibitors of ITGB3 + JNK or ITGB3 + IGF1R." (PMID 34106558, 2021). "The verified universal EV marker ITGB3 serves as a receptor for components of the ECM, including FN1, and plays roles in the progression of different cancer-associated processes, including initiation, proliferation, survival, migration, and invasion." (PMID 32916986, 2020). "As Itgav has been shown to partner with ITGB3 to form a heterodimeric integrin receptor in a variety of cells, including a number of cancers, we investigated the expression of ITGB3 in the stem cell sub-populations." (PMID 32735820, 2020). "ITGB3 belongs to the integrin family, and integrin has some important functions in the occurrence and development of malignant tumors." (PMID 31505835, 2019). "We also confirmed that depletion of ITGB3 sensitized cancer cells to conventional chemotherapeutic drugs by modulating the NF-κB signaling pathway." (PMID 30563517, 2018). "The top five up-regulated cancer stemness associated genes include: SNAI2 (SLUG) (8.2 folds), SOX9 (6.4 folds), ITGB3 (integrin β3) (5.4 folds), CD44 (4.3 folds) and MET (2.9 folds) (DU145FP vs. DU145WT)." (PMID 28698547, 2017). "By inhibiting ITGB3 expression in cancer cells via infection with viral shRNA, we observed reduced migration, as expected, and increased apoptosis, but these effects were surprisingly more significant in hypoxia." (PMID 29383126, 2017). "In a mouse model of spontaneous tumorigenesis caused by WNT1 overexpression, the luminal epithelial progenitor marker ITGB3 identified a highly tumorigenic cancer stem cell population." (PMID 27833078, 2016). "One of the most well-studied integrins in cancer was oncogenic integrin αvβ3, of which ITGB3 (also known as β3 integrin) was a key component." (PMID 27833078, 2016). "However, the ITGB3+ population only increased within mesenchymal EpCAMneg and full mesenchymal cancer cells, suggesting that the enrichment of ITGB3+ cancer cells in mixed cSCCs is a consequence of the emergence of EpCAMneg cancer cells in these tumors." (PMID 39075581, 2024). "Targeting cancer stem cell properties and EMT, which are linked to resistance, could also improve patient outcomes, and investigating ITGB3′s role in these processes may uncover new therapeutic targets." (PMID 39857240, 2024). "Cancer cell deacetylation of ITGB3‐vWA domain‐K416 was correlative with a poor prognosis." (PMID 36453571, 2023). "The aberrant expression and distribution of ITGB3 is reported to facilatate cancer metastasis." (PMID 37040507, 2023). "The β3 integrin (ITGB3) is known to play an important role in cancer metastasis." (PMID 33456563, 2021). "ITGB3 is an important molecule involved in cell survival, proliferation and cancer metastasis." (PMID 34663331, 2021). "Furthermore, the Pathway analysis based on KEGG method indicated that, among the 10 differentially expressed mRNAs, ITGB3, TGFβ2 and TNC were linked to the pathway of MicroRNAs in Cancer." (PMID 33100909, 2020). "In addition, integrin subunit beta 3 (ITGB3) was identified as a target to overcome chemoresistance in mesenchymal lung cancer, and inhibition of ITGB3 sensitizes cancer cells to chemotherapy by regulating the NF-κB pathway." (PMID 32232000, 2020).
cancer (continued). "Thus, ITGB3 has a central role in intracellular communication via extracellular vesicles, proposed to be critical for cancer metastasis." (PMID 32848136, 2020). "Although multiple signaling pathways coordinately regulate cancer stemness, the dysregulation of miR-483-3p may play a partial role in the ITGB3-mediated regulation of stemness in cancer, since ITGB3 was reported to drive cancer stemness." (PMID 31861937, 2019). "First of all, ITGB3 has been found up-regulated in both cancer and endothelial cells." (PMID 30559931, 2018). "Similarly, mutations in ITGB1, ITGB3, and ITGB7 can alter their interaction with calpain, which may affect the focal adhesion of cancer cells and therefore needs to be validated further via a multidisciplinary approach." (PMID 40362482, 2025). "Also, the direct regulation of PAX8 is not only important in controlling the protein levels of ITGB3 but also in turn affects the αvβ3 heterodimer expression on the plasma membrane which could alter the cancer cell migratory properties." (PMID 31832016, 2019). "We also observed increased mRNA expression of one of CYR61’s receptors—ITGB3/CD61—which is a marker of late EMT stages and cancer stem cells." (PMID 40936697, 2025). "Flow cytometry analyses showed that the percentage of ITGAV+ and ITGB3+ cancer cells was significantly higher in mixed compared with epithelial cSCCs, and that most cancer cells in mesenchymal cSCCs were ITGAV+ and ITGB3+." (PMID 39075581, 2024). "In particular, engagement with integrins, namely β1-(ITGB1) or β3-integrin (ITGB3), has been shown to enhance IGF-1R signaling in cancer cell models, fibroblasts, and endothelial cells." (PMID 39608716, 2024). "Downregulation of TLN1, ITGB3, and TUBA4A with simultaneous upregulation of HSPG2 protein were observed in cancer samples compared to healthy controls." (PMID 37241967, 2023). "ITGB3 is a regulator of the PI3K/AKT/mTOR pathway and has roles in cancer and extracellular vesicles that induce cell signaling." (PMID 34831441, 2021). "To explore a chemical compound to target ITGB3, we used CMAP, an approach that has been used widely in cancer drug discovery, to screen a candidate drug." (PMID 34805144, 2021). "According to the database annotation, universal EV proteins (CDC42, GNAI2, ITGB3, TLN1, and TUBA4A) are involved in platelet activation that help cancer cells escape immune surveillance and provide a prometastatic microenvironment." (PMID 32916986, 2020). "Cancer patients with high CCN1 expression have poor survival outcomes and positive correlation with ITGAV and ITGB3 and high YAP/WWTR1." (PMID 31429823, 2019). "The novel ADAR1-dependent and RNA-editing-independent regulation of invasion, mediated by ITGB3, strongly points to a central involvement of ADAR1 in cancer progression and metastasis." (PMID 29855470, 2018). "Cancer cells interact with fibronectin via integrins: ITGAV, ITGA5, ITGB1 and ITGB3." (PMID 40636307, 2025). "As we and others have shown for ITGB3, VEGFA has been detected in cancer cell–derived EVs." (PMID 40662366, 2025). "Likewise, EpCAM+ITGAV+ cancer cells expressed higher levels of the plasticity genes Axl, Tnc, Itgb3, and Vcam1 than EpCAM+ITGAV− cancer cells, indicating that EpCAM+ITGAV+ cancer cells exhibit a hybrid E/M phenotype." (PMID 39075581, 2024). "As for the DNA methylation, the cancers and the corresponding genes with hypermethylation were as follows: BRCA: VWF and ITGB3; COAD: QKI, DUSP9, and CNKSR2; KIRC: CNKSR1; PRAD: VWF, LMNA, and ITGB3; UCEC: ITGB3 and APBBAIP." (PMID 38217548, 2024). "Accordingly, ITGB3 marker is not suitable for differentiating full epithelial from epithelial plastic cancer cells." (PMID 39075581, 2024). "The promoting effect of axes HOXA11-AS/miR-124/EZH2 (enhancer of zeste homolog 2 of polycomb group protein), HOXA11-AS/miR-124-3p/ITGB3 (integrin β3), and HOXA11-AS/miR-124/Sp1 (Sp1 transcriptional factor) on cancer cell proliferation, migration, invasion was shown in vitro." (PMID 36362406, 2022).
cancer (continued). "MiRNA-let-7c-5p, the miRNA studied in our research, has been widely reported in different cancer types, it can mediate the pathogenesis progression of NSCLC by targeting ITGB3 and MAP4K3 31, and promote the sensitivity of LUAD cells to EGFR-TKIs by inhibiting the WNT pathway." (PMID 36046641, 2022). "Furthermore, we found that some ITGs such as ITGA3, ITGA6 ITGA11, ITGB4, ITGB6, etc. were frequently upregulated in human cancers, whereas ITGs including ITGA1, ITGA7, ITGA8, ITGA9 and ITGB3, etc. were usually downregulated." (PMID 34222028, 2021). "ITGB3 and BMPR2 genes were key regulators of cell migration and invasion of cancer cells." (PMID 32315343, 2020). "This suggests that ITGB3 is important for cell migration and survival in both cancer and non-malignant cells, but particularly under hypoxic conditions." (PMID 29383126, 2017). "From various cancer formation and metastasis signals, it can be seen that a set of matrix metalloproteases (MMPs) (MMP27, MMP23B, THBS2, MMP13, MMP11) as well as the MMPs receptor ITGB3 were inhibited in GX0101-infected CEFs." (PMID 27200301, 2016). "Cancer Pathway cDNA microarray analysis revealed that DACT1α down-regulated cell adhesion receptors from the integrin family including ITGA1, ITGA2, ITGA3 and ITGB3." (PMID 27833078, 2016). "However, a direct mechanistic link between SERPINA1 and the ubiquitination-dependent regulation of ITGB3 has not been established in any cancer type." (PMID 41467954, 2025). "ITGB3-+ IGF1R-targeting drugs (cilengitide + linsitinib) could be used as an effective therapy for suppressing the adaptive formation of the HDGF-LGR5 protein complex, which enhanced cancer stemness during MAPKi stress." (PMID 34106558, 2021). "In this study, we showed that ITGB3 is translationally activated upon hypoxia and hypoxia + PP242 in cancer and non-tumourigenic breast epithelial cells and that this protein synthesis activation was dependent on eIF4E." (PMID 29383126, 2017). "We measured cell migration in control and ITGB3-silenced MDA-MB-231 cells with or without treatment with TGF-β, a well-known stimulator of EMT and migration in cancer cells." (PMID 29383126, 2017). "Importantly, we demonstrate that the upregulation of ITGB3 requires accessible chromatin at ITGB3 enhancers to allow for STAT3 binding, but not all cancer cells or tumors are capable of this adaptive response due to inaccessible enhancers." (PMID 40701148, 2025). "Furthermore, by stratifying the analysis according to cancer stage (III/IV vs. I/II and I/II/III vs. IV), ITGB3 rs5918 significantly impacted OS among patients without distant metastases (I/II/III vs. IV; log-rank test, P = 0.021) but not among their counterparts (log-rank test, P = 0.147)." (PMID 40425987, 2025). "In the overall cohort, ZFPM2 rs4734879, SLC19 A2 rs2038024, ITGB3 rs5918 and GSR rs3779647 did not exhibit a significant impact on five-year DFS, regardless of genetic model (additive, recessive or dominant), sex (male vs. female) and cancer stage (III/IV vs. I/II or I/II/III vs. IV)." (PMID 40425987, 2025).
infection (30 papers, 2010 to 2025). The state of being infected such as from the introduction of a foreign agent such as serum, vaccine, antigenic substance or organism. "The transcript levels of the myeloid lineage-related genes RUNX1, vWF, ITGB3, PU.1 and GM-CSF were significantly increased by 7 days of Omicron PsV infection." (PMID 40025168, 2025). "Following infection with the ITGB3-targeting lentivirus, ITGB3 expression was determined in Jurkat and MOLT-4 cells by qRT-PCR and Western blot, respectively." (PMID 36944577, 2023). "After infection with ITGB3-OE plasmids, the expression of ITGB3 significantly increased compared with that of NC." (PMID 37760946, 2023). "Previous studies have shown a link between ITGB3 expression and infection of porcine cells by classical swine fever virus strains." (PMID 33669854, 2021). "How LASV is affecting the function of ITGB3 in vivo remains to be explored, and the protection seen in the mouse model, combined with the increased expression in human PBMC exposed to a pathogenic virus, suggests that ITGB3 is playing an important role in arenavirus infections." (PMID 24921924, 2014). "ANDV infection showed upregulation of cell type-specific viral entry genes (Calu-3: CD55 and ITGB3; hPSC-astrocytes: MERTK and VEGFA)." (PMID 40857262, 2025). "Relative gene expression of ITGB1, ITGB2 ITGB3 and CAV-1 in THP-1 or HUVEC were analysed by comparing treatment of 4h leptospires infection and non-infection." (PMID 36137081, 2022). "Although, most shared altered host proteins between both BVDV biotypes showed the same type of change, integrin alpha 2b (ITGA2B) and integrin beta 3 (ITGB3) were down- regulated by ncp BVDV and up- regulated by cp BVDV infection." (PMID 20946620, 2010). "Two of these genes, ITGB3 (logFC of 3.77) and ITGA2B (logFC of 1.58), were upregulated in the cells challenged with ETEC, while this upregulation was abolished by pretreating cells with EPS before infection." (PMID 32234079, 2020). "Interestingly, ITGA2B and integrin beta 3 (ITGB3) were found to be downregulated in PBMCs in infection by non-cytopathic bovine viral diarrhea virus (ncp BVDV) and upregulated by the cytopathic biotype (cp BVDV) in proteomic studies." (PMID 28475627, 2017).
cardiovascular disease (10 papers, 2007 to 2024). "The purpose of this study was to investigate the effects of the SH2B3, MTHFD1L, GGCX, and ITGB3 gene variants on the efficacy of warfarin treatment and its effects on the risk of cardiovascular disorders in Jordanian patients." (PMID 32916786, 2020). "The genotypes of SH2B3, MTHFD1L, GGCX, and ITGB3 polymorphisms, plus clinical data for the participants, were evaluated to investigate their effects on the risk of cardiovascular disease and warfarin sensitivity and responsiveness during the initial phase treatment." (PMID 32916786, 2020). "However, it was discovered that the ITGB3 gene was a highly polymorphic region, and some of these polymorphisms were associated with cardiovascular diseases." (PMID 32916786, 2020). "Given, the important role of ITGB3, our findings underscore the importance of sdLDL particles in cardiovascular disease mechanisms, highlighting their role in exacerbating the harmful effects of elevated LDL-C levels." (PMID 39028281, 2024). "From this result, two lncRNAs AP001033.3–201 and AC068234.2–202, and two potential target genes, integrin beta-3 (ITGB3) and thromboxane A2 receptor (TBXA2R), were identified to be associated with cardiovascular disease and involved in the platelet activation pathway." (PMID 33172104, 2020). "Finally, the study results indicated that ITGB3 and TBXA2R were both differentially expressed between the two groups and were both related to the platelet activation pathway and cardiovascular disease in a GO enrichment analysis." (PMID 32723322, 2020).
hematologic malignancy (2 papers, 2022 to 2025). "However, few studies have been performed for the clinical implication of ITGB3 in hematologic malignancy patients, participants in MM patients." (PMID 34635968, 2022).
autosomal recessive disease (1 paper, 2014). Autosomal recessive form of disease. "As GT is an autosomal recessive disease, patients are mostly compound heterozygotes for ITGA2B or ITGB3 mutations in the absence of consanguinity." (PMID 25539746, 2014).